SRC (SRC proto-oncogene, non-receptor tyrosine kinase)
Diseases named in the same sentence as SRC in open-access papers (continued):
Sharing a sentence is not in itself a finding about the gene and the disease.
infection (29 papers, 2013 to 2025). The state of being infected such as from the introduction of a foreign agent such as serum, vaccine, antigenic substance or organism. "Although most of the cells were SeV-positive after infection, the uninfected cells, if any, were removed by G418 selection to ensure more accurate comparison of the efficacy of SrC switch installed into different SeVdp vectors." (PMID 38229076, 2024). "In addition, SRC may be involved in the clearance of pathogens that cause infection in the body." (PMID 39885929, 2024). "ALKBH5 knockdown increased the levels of the IL-1β, CSF3, TGM2, and SRC transcripts during infection by P. aeruginosa, C. diphtheriae, WT HSV-1, or the ICP34.5 mutant virus." (PMID 36625590, 2023). "CagA bridges the T4SS to integrin α5 β1 on host cells, which activates the SRC and focal adhesion kinase, which ensures that CagA is phosphorylated at the site of infection." (PMID 32993565, 2020). "The SRC inhibitor blocked SRC phosphorylation of FAK Y576/577 within 30 min of infection, indicating inhibition of SRC kinase." (PMID 27803182, 2016). "Together, these data showed that although several signaling pathways are activated by MuPyV binding and entry, only the PI3K and FAK/SRC pathways are required for the initial steps of infection." (PMID 27803182, 2016). "Similar to the PI3K inhibitor results, inhibition of the FAK or SRC kinases during virus entry blocked infection." (PMID 27803182, 2016). "Because the PI3K and FAK/SRC pathway are both required for infection, it is possible that these pathways are undergoing synergistic cross talk, with both contributing to a single step of infection." (PMID 27803182, 2016). "We used FAK inhibitor 14 (FAK14) and a SRC family kinase inhibitor (AZM475271) to determine whether FAK/SRC activation is required for infection." (PMID 27803182, 2016). "In the context of infection by porcine epidemic diarrhea virus (PEDV), SRC plays a pivotal role in the coordination and promotion of cell signaling pathways." (PMID 39205203, 2024). "Further studies investigating how microtubules are recruited to the plasma membrane during infection, as well as the role of FAK/SRC in this process, could elucidate an important step in intracellular virus trafficking." (PMID 27803182, 2016). "Taken together, these results indicate that while the PI3K and FAK/SRC pathways are both required for infection, they are not synergistic and likely contribute to distinct steps of virus entry." (PMID 27803182, 2016). "However, there were elevated levels of phosphorylated SRC in the FAK−/− MEFs, as previously reported, although this activation was insufficient to restore infection of these cells." (PMID 27803182, 2016). "Inhibition of FAK/SRC post-virus entry (2 to 4 h) resulted in decreased infection, but not to the extent seen if added during virus entry." (PMID 27803182, 2016). "SRC inhibition blocked infection but not MuPyV internalization, suggesting that this pathway may contribute to a subsequent step in the virus life cycle, such as virus trafficking." (PMID 27803182, 2016).
cardiovascular diseases (5 papers, 2016 to 2025). "SRC is required for mechanical stress (MS)-induced cardiomyocyte hypertrophy and activates various signaling pathways involved in cardiovascular diseases." (PMID 38326862, 2024). "SRC is a potential therapeutic molecule for reducing morbidity and mortality related to cardiovascular diseases." (PMID 38515732, 2024). "The role of SRC in cardiovascular diseases was also observed by some researches." (PMID 39936089, 2025). "Among genes where AS affected the domain structure, we also found CDK8 (cyclin-dependent kinase 8) and SRC (SRC proto-oncogene, non-receptor tyrosine kinase), which are associated with cardiovascular disease and cardiac remodeling, respectively." (PMID 40337913, 2025).
neurodegenerative disease (4 papers, 2023 to 2024). A disorder of the central nervous system characterized by gradual and progressive loss of neural tissue and neurologic function. "SRC has been found to be closely associated with neuronal damage and inflammatory responses, participating in the occurrence and development of degenerative diseases." (PMID 39062794, 2024).
cardiac disease (3 papers, 2016 to 2018). "Although normal cells operate at a basal level of OCR, the SRC provides ATP under stress conditions that enhance the cellular energetic demand and its exhaustion has been linked to induction of apoptosis, to neurodegeneration and to heart disease." (PMID 29651165, 2018).
colorectal (3 papers, 2021 to 2025). "With the aim of further validating the variant-induced upregulation of SRC activity and investigating the respective impact on colorectal carcinogenesis, key components of known SRC signaling pathways were checked for altered protein expression." (PMID 33916261, 2021).
blood cancer (1 paper, 2025). "In 2018, Lee and her team discovered that in addition to being activated by ER stress, SRC actively promoted cell-surface relocalization of ER chaperones in a variety of solid and blood cancer cell lines, and importantly, SRC was both necessary and sufficient for this process." (PMID 40699920, 2025).
psychiatric diseases (1 paper, 2023). "TSPAN7 knockout causes ASD-like phenotypes in rats through the integrin β1/FAK/SRC signal pathway, which provides novel insights into the role of TSPAN7 in psychiatric diseases, highlighting SRC as a potential target." (PMID 36625203, 2023).
SRC also shares sentences with these, for which no sentence is quoted: adenocarcinoma (6 papers); type 2 diabetes (6); lung squamous cell carcinoma (5); prostate tumors (5); skin cancer (5); hematologic diseases (4); liver disease (4); pancreatic adenocarcinoma (4); retinopathy (4); type 1 diabetes (4); actinic keratosis (3); atrial fibrillation (3); cardiomyopathy (3); esophageal cancer (3); fibrosis (3); idiopathic pulmonary fibrosis (3); inflammatory bowel disease (3); metabolic disorders (3); myelofibrosis (3); rheumatoid arthritis (3); anemia (2); Arthritis (2); Brain Tumor (2); breast adenocarcinoma (2); chronic kidney disease (2); clear cell renal cell carcinoma (2); colon polyps (2); coronary artery disease (2); cytomegalovirus infection (2); dilated cardiomyopathy (2).
A further 125 diseases each share a sentence with SRC in 2 papers or fewer.